ENSG00000227193 (novel transcript)
Gene: Long non-coding RNA gene on chromosome 1 (121,097,704 to 121,147,596, forward strand). Ensembl gene ENSG00000227193.
Gene Ontology:
Biological process: mRNA 3'-end processing by stem-loop binding and cleavage